PRDX6 (peroxiredoxin 6)
Diseases named in the same sentence as PRDX6 in open-access papers (continued):
Sharing a sentence is not in itself a finding about the gene and the disease.
epilepsy (1 paper, 2024). A brain disorder characterized by episodes of abnormally increased neuronal discharge resulting in transient episodes of sensory or motor neurological dysfunction, or psychic dysfunction. "In our data, serum levels of PRDX6 were notably decreased in patients with DRE compared with controls, suggesting the heterogeneity of different types of epilepsy disorders in different species." (PMID 38585359, 2024).
fungal keratitis (1 paper, 2017). "The average ratios of the expression levels of the Hmox1, Nos3, Hif1a, Sod2, Sod3, and Gpx2 genes increased more than 2-fold (p < 0.05) at day 1 p.i. in the fungal keratitis model, whereas the expression ratios of the Hif1an and Prdx6 genes decreased more than 2-fold (p < 0.05)." (PMID 28874754, 2017).
Hepatic steatosis (1 paper, 2022). Steatosis is a term used to denote lipid accumulation within hepatocytes. "Though the concept is new, increased PRDX6 expression protected mice from developing hepatic steatosis." (PMID 34327606, 2022). "Recent studies suggest that peroxiredoxin 6 (PRDX6) may provide an anti-steatotic effect during fatty liver disease, mainly through elimination of oxidants." (PMID 34327606, 2022). "Accordingly, we found an inverse relationship between PRDX6 abundance and hepatic TAG levels, suggesting that PRDX6 abundance may present with decreased liver TAG levels and reduced hepatic steatosis." (PMID 34327606, 2022).
hepatoblastoma (1 paper, 2019). Hepatoblastoma (HB) is a malignant hepatic tumor and is the most common pediatric liver cancer. "We have down-regulated Prdx6 with specific siRNA in hepatoblastoma HepG2 cells to study its role in cell proliferation, redox homeostasis, and metabolic programming." (PMID 31652719, 2019).
inflammatory bowel disease (1 paper, 2019). A spectrum of small and large bowel inflammatory diseases of unknown etiology. "On one hand, inflammation can often lower expression of Prdx6, while on the other, it is overexpressed in some inflammatory pathologies, such as inflammatory bowel disease (IBD)." (PMID 30871234, 2019).
insulinoma (1 paper, 2020). "Meanwhile, in the rat insulinoma cell line, the recombinant PRDX6 attenuated effect of exogenous proinflammatory cytokines on the ROS production and activation of NF-κB and JNK signaling pathways." (PMID 32908936, 2020).
kidney cancer (1 paper, 2021). Primary or metastatic malignant neoplasm involving the kidney. "Increased or decreased levels of PRDXs mRNA expression levels were found among 33 tumor types, such as PRDX1, PRDX2, PRDX4 and PRDX5 increased in several cancer types, while PRDX3 and PRDX6 decreased in there types of kidney cancer (KIRP, KIRC and KICH)." (PMID 34246267, 2021). "Notably, when compared to adjacent or normal tissues, PRDX1, PRDX2, PRDX4 and PRDX5 were significantly up-regulated expression in several cancer types (UCEC, READ, BLCA, BRCA, CHOL, COAD, LIHC, THCA), while PRDX3 and PRDX6 were down-regulated expression in kidney cancers." (PMID 34246267, 2021).
Leber congenital amaurosis (1 paper, 2022). Leber congenital amaurosis (LCA) is a retinal dystrophy defined by blindness and responses to electrophysiological stimulation (Ganzfeld electroretinogram (ERG)) below threshold, associated with severe visual impairment within the first year of life. "In a mouse model of Leber congenital amaurosis (LCA) after gene therapy with AAV-delivered RPE65, a proteomic study found PRDX6 was significantly upregulated among 39 other proteins." (PMID 36274523, 2022).
leukaemia (1 paper, 2024). "In addition, we also found some leukaemia‐specific proteins, oncogenes (COL2A1, CLIP1, NUMA1 and GALK1), and stem cell‐regulated proteins (ACAN, VCAN, COMP and PRDX6)." (PMID 38499475, 2024).
liver dysfunction (1 paper, 2023). "Furthermore, in this study, the authors observed that mice lacking Prdx6 were more likely to develop severe liver dysfunction." (PMID 36674516, 2023).
lung squamous cell carcinoma (1 paper, 2014). "Moreover, PRDX6 was found at higher levels in lung squamous cell carcinoma patients." (PMID 24618722, 2014).
lupus nephritis (1 paper, 2024). Glomerulonephritis in the context of systemic lupus erythematosus. "ALCAM, HPX, and PRDX6 showed significant diagnostic values, especially for lupus nephritis (LN), with areas under the receiver operating characteristic curve for LN was 0.850 for ALCAM (95% CI, 0.778–0.921), 0.781 for HPX (95% CI, 0.695–0.867), and 0.714 for PRDX6 (95% CI, 0.617–0.812)." (PMID 38915417, 2024).
malignant mesothelioma (1 paper, 2007). A malignant neoplasm of the pleura or peritoneum, arising from mesothelial cells. "Furthermore, overexpression of PRDX6 was found in malignant mesothelioma of the lung." (PMID 17980029, 2007).
mastitis (1 paper, 2025). Inflammation of breast tissue during lactation or postpartum due to an obstructed duct or infection. "PCR-DNA sequence revealed nucleotide sequence differences in the PRDX6 and NDUFS6 genes among control and mastitis-affected she-camels." (PMID 40711280, 2025).
metastasis (1 paper, 2022). The spread or migration of cancer cells from one part of the body (where they first appeared) to another. "Statistical analysis was performed to determine the relationship between PRDX6 expression level and age, sex, histological type, tumor size, tumor number, lymph node metastasis, vascular invasion, perineural invasion, distant metastasis and TNM stage." (PMID 36209344, 2022).
muscle atrophy (1 paper, 2020). The loss of muscle tissue due to inactivity or disease. "Muscle atrophy was also present in Prdx6-/- mice by the increase in Muscle RING finger 1 (MuRF1) levels and proteins ubiquitination associated to a reduction in muscle strength." (PMID 32316601, 2020).
oral epithelial dysplasia (1 paper, 2013). "The data also showed us that the level of PPIA, Prdx6, and CD147 in OSCC was significant higher when compared with oral epithelial dysplasia and/or normal oral mucosa (P<0.05)." (PMID 24386210, 2013).
oropharyngeal squamous cell carcinomas (1 paper, 2025). "Thus, we have investigated if a relationship between tumor expression of NRF2, peroxiredoxin 6, and survival in a cohort of patients with advanced non-HPV induced oropharyngeal squamous cell carcinomas treated with surgery followed by adjuvant radiation therapy exists." (PMID 41187427, 2025).
peripheral arterial disease (1 paper, 2022). A disorder of the arteries supplying the upper and lower extremity and the visceral organs. "The increased expression of Prdx6 has been demonstrated in various injury models and patients with peripheral arterial disease." (PMID 36311744, 2022).
pneumonia (1 paper, 2025). An acute, acute and chronic, or chronic inflammation focally or diffusely affecting the lung parenchyma, caused by an infection in one or both of the lungs (by bacteria, viruses, fungi, or mycoplasma.). "Using PCR-DNA sequence verdicts, the IL-1α (356-bp), IL-1β (423-bp), IL-6 (384-bp), TNFα (490-bp), IL-10 (306-bp), IFN-γ (321-bp), PRDX6 (434-bp), ATG7 (416-bp), NDUFS6 (405-bp), and NOX4 (396-bp) genes were found to have different SNPs in the amplified DNA bases linked to pneumonia." (PMID 40711280, 2025). "Our investigation used a PCR-DNA-sequencing procedure to illustrate the difference in immunological (IL-1α, IL1B, IL6, TNF-α, IL10, and IFN-γ) and antioxidant (PRDX6, ATG7, NDUFS6, and NOX4) genes in calves with pneumonia and healthy calves." (PMID 40711280, 2025).
polycystic ovary syndrome (1 paper, 2020). A disorder that manifests as multiple cysts on the ovaries. "In human ffEVs, 86 proteins were differentially expressed in patients with polycystic ovary syndrome relative to controls, some of which were also identified in our study (APMAP, PRDX6, isocitrate and malate dehydrogenases, etc)." (PMID 33330709, 2020).
prostate adenocarcinoma (1 paper, 2007). "Ouyang and colleagues found that progression of prostate adenocarcinoma was correlated to the deregulation of antioxidants, including PRDX6, in Nkx3.1 mutant mice." (PMID 17980029, 2007).
renal fibrosis (1 paper, 2016). A final common manifestation of a wide variety of chronic kidney diseases characterized by glomerulosclerosis and tubulointerstitial fibrosis. "To determine involvement of Prdxs in renal fibrosis, we analyzed the expression pattern of Prdxs isotypes (Prdx1, Prdx2, Prdx3, Prdx4, Prdx5, and Prdx6) in the cortex/outer stripe of outer medulla of UUO kidney." (PMID 26872211, 2016). "Among the isotypes, mitochondrial forms of Prdxs (Prdx3 and Prdx5) and Prdx6 were decreased with the progression of renal fibrosis." (PMID 26872211, 2016). "It suggests that major mitochondrial Prdxs and Prdx6 could be involved in the pathophysiology of renal fibrosis." (PMID 26872211, 2016). "However, the involvement of Prdx3 and Prdx6 in renal fibrosis should be further elucidated." (PMID 26872211, 2016).
retinal diseases (1 paper, 2023). "Therefore, PRDX6 shows promise as a therapeutic target for the prevention of RPE cell damage caused by oxidative stress associated with retinal diseases." (PMID 37529008, 2023).
small cell lung carcinoma (1 paper, 2025). Small cell lung cancer (SCLC) is a highly aggressive malignant neoplasm, accounting for 10-15% of lung cancer cases, characterized byrapid growth, and early metastasis. "Furthermore, recent research indicates that 18β-GRA exerts anti-small cell lung cancer effects by promoting peroxiredoxin-6 (Prdx6) and caspase-3-mediated mitochondrial apoptosis." (PMID 41561975, 2025).
squamous cervical cancer (1 paper, 2020). "Furthermore, the overexpression of PRDX6 stimulated the proliferation, migration and invasion of cervical squamous cancer cells, and suppressed cell apoptosis." (PMID 32201510, 2020). "Thus, the purpose of this study was to explore the functional impacts of PRDX6 gene on the biological behavior of cervical squamous cancer cells." (PMID 32201510, 2020). "Thus, the purpose of this study was to explore the functional impacts of the PRDX6 gene on the biological behavior of cervical squamous cancer cells." (PMID 32201510, 2020).
stress-related disorder (1 paper, 2021). Stress-related disorders are mental health disorders that are a result of an atypical response to both short and long-term anxiety due to physical, mental, or emotional stress. "Furthermore, enhanced stress susceptibility of the Prdx6−/− mice suggests that PRDX6 can be a therapeutic target for treating stress-related disorders such as PTSD." (PMID 34573048, 2021). "Several studies have demonstrated the correlation between PRDX6 expression level and stress-related disorders." (PMID 34573048, 2021). "PRDX6 is involved in various forms of stress-related disorders." (PMID 34573048, 2021).
thyroid neoplasms (1 paper, 2023). "The PRDX6 expression level was also shown to be repressed in PTC patients in their study compared to patients with other thyroid neoplasms." (PMID 37692064, 2023).
transient cerebral ischemia (1 paper, 2017). "We next investigated the role of iPLA2 activity of Prdx6 in transient cerebral ischemia and the potential mechanism underlying the observations." (PMID 28424593, 2017).
viral infection (1 paper, 2012). "One possible explanation for the reduction in Cat and Prdx6 is that cells that normally express these antioxidants are cleared due to viral infection." (PMID 22355371, 2012).
vitiligo (1 paper, 2024). Generalized well circumscribed patches of leukoderma that are generally distributed over symmetric body locations and is due to autoimmune destruction of melanocytes. "This analysis showed peroxiredoxin-6 (PRDX6) and apolipoprotein L1 (APOL1) to be downregulated in patients with progressive and stable vitiligo compared to healthy controls, with in both cases the protein being more downregulated in progressive vitiligo compared to stable vitiligo." (PMID 38715599, 2024).
cancer (74 papers, 2007 to 2026). A tumor composed of atypical neoplastic, often pleomorphic cells that invade other tissues. "High levels of Prdx6 are associated with increased metastasis and resistance to chemotherapy, rendering Prdx6 a therapeutic target for treatment of a broad range of cancers." (PMID 41702017, 2025). "circ-231 promotes the unwinding of 5′ UTRs of TPI1 and PRDX6 mRNAs, which is associated with the migration and proliferation of cancer cells, suggesting that circ-231 plays a critical role in cancer cells." (PMID 38577609, 2024). "Elevated levels of PRDX6 expression have been shown to be associated with a variety of human cancers, among which lung and breast." (PMID 36361777, 2022). "PRDX2 and PRDX6 encoding peroxiredoxins were reported to be associated with chemoresistance in cancer." (PMID 30925767, 2019). "Moreover, peroxiredoxin 6 is involved in the regulation of cell migration and is also associated with cancer progression." (PMID 41187427, 2025). "In contrast, PRDX6 deficiency leads to lipid peroxidation and ROS accumulation, which can activate various signaling pathways, including ferroptosis, ultimately resulting in cancer cell death." (PMID 40583735, 2025). "Despite nearly two decades of effort, it remains unknown regarding the mechanisms underlying the generation of PRDX6 antibody and its functional implications in cancer pathogenesis." (PMID 40298631, 2025). "PRDX6 has been linked to various pathologies including cancer." (PMID 39601357, 2024). "PRDX6 expression is associated with poor prognosis in cancers of multiple tissue origins." (PMID 27484502, 2016). "Moreover, loss of PRDX6 reduced the amount of selenoproteins in several human cancer cell lines, indicating that the role of PRDX6 is conserved across many cancer types." (PMID 38867112, 2024). "Consistent with its tumor-suppressive role, miR-24-3p has been reported to inhibit cancer cell migration and invasion by targeting key regulators such as Prdx6." (PMID 41303548, 2025). "Only one study showed that peroxiredoxin 6 is expressed at lower levels in buccal mucosa than in tumor tissue, highlighting the role of antioxidant enzymes in cancer development." (PMID 41187427, 2025). "The proposed mechanisms explaining the role of NRF2 and PRDX6 in therapeutic resistance are partly based on data from other cancer types (lung, breast, ovarian)." (PMID 41187427, 2025). "The recently discovered antioxidant enzyme peroxiredoxin 6 (Prdx6) was observed to downregulate ferroptosis in various cancer cell lines, such as H1299, A549 and 293FT cells." (PMID 41463452, 2025). "With advances in tumor immunology, further studies are warranted to elucidate the role of PRDX6 and its corresponding antibodies in tumorigenesis and cancer progression." (PMID 40298631, 2025). "A higher tissue content of PRDX6 is often correlated with lower overall survival rates and poorer outcomes, but paradox findings exist in certain cancer types." (PMID 40298631, 2025). "ROS exert cytotoxic effects on cancer cells, while PRDX6 detoxifies ROS and maintains cellular homeostasis." (PMID 40583735, 2025). "The phospholipase A2 activity of PRDX6 promotes tumor necrosis factor alpha‐induced cancer cell death in HCC." (PMID 37994394, 2024). "Peroxiredoxin 6, an antioxidant protein, promotes cancer cell proliferation in an oxidative stress environment." (PMID 38249992, 2024). "PRDX6 can favor ROS tolerance, contributing to cancer hallmarks and preventing ROS-derived cytotoxicity." (PMID 39061949, 2024). "The upregulation of antioxidants in both kinds of cancer cells under zinc exposure, such as peroxiredoxin 6, would benefit cancer cell growth in response to the change of environmental conditions." (PMID 38249992, 2024).
cancer (continued). "It is expected that the drastic decrease in sphingomyelins and DHA provoked by loss of PRDX6 could contribute to destabilization of lipid rafts, although further experimental evidence would be needed to confirm this and its possible relevance in the context of cancer treatment." (PMID 39601357, 2024). "Previous studies have shown that PRDX6 is widely involved in the proliferation, migration, and invasion of a variety of cancer cells." (PMID 38544826, 2024). "PRDX6 is present in various cancers and can reduce H2O2, short-chain hydroperoxides, and PLOOH in the cell membrane with the help of GSH, thus restoring cancer cell membranes." (PMID 38674143, 2024). "Elevated levels of PRDX6 have been described in a wide variety of human cancers and its overexpression promotes invasion and metastasis in lung cancer and lung tumor growth in mice through activation of JAK2/STAT3 signaling." (PMID 39601357, 2024). "The findings demonstrate that peroxiredoxin 6 is related to the cancer development and stress response while peroxiredoxin 2 is likely more relevant to stress response." (PMID 38249992, 2024). "Further studies on PRDX6 gene regulation in human cancers would help us to understand more of its role in cancer development." (PMID 38544826, 2024). "PRDX6 has been implicated in cell migration through interaction with NOX1 in HCT-116 cancer cells, specifically through aiPLA2 activity." (PMID 37371884, 2023). "Previous studies showed elevated expression levels of PRDX6 in a variety of metastatic potential, and poor prognosis cancers." (PMID 37501157, 2023). "Some evidence has linked PRDX6 to EMT, but additional research on its mechanism of metastatic action is needed to identify novel therapeutic targets and strategies against cancer." (PMID 37371884, 2023). "For instance, sumoylation of SIRT1 promotes the survival of normal and cancer cells, while sumoylation of protein peroxiredoxin 6 impairs its cell protective function." (PMID 37828576, 2023). "Accumulated evidence suggests that PRDX6 exerts specific functions in cancer progression, affecting cell growth, survival, migration, differentiation, invasiveness, and metastasis." (PMID 36361777, 2022). "To further mine ZDHHCs correlated with PRDX6, we performed the Pearson’s correlation analysis for PRDX6 and ZDHHCs by the proteomic data of human normal and cancer tissues." (PMID 36120430, 2022). "So, our findings demonstrate the inhibitory effects of FTH1 on PRDX6 and suggest a new potential therapeutic target for the development of novel therapeutic strategies for the treatments of such cancers overexpressing PRDX6." (PMID 36361777, 2022). "PRDX6 is expressed in ICC cancer cells and macrophages, the latter being a key cellular liver component for maintaining liver homeostasis." (PMID 36209344, 2022). "It has been demonstrated that PRDX6 is highly expressed in human cancer cells and plays a critical role in cancer development." (PMID 36361777, 2022). "High PRDX6 levels promote cancer progression, migration, invasiveness and resistance to radiotherapy and chemotherapy." (PMID 36209344, 2022). "It has been demonstrated that PRDX6 promotes cell proliferation and inhibits cancer cell apoptosis; its peroxidase activity promotes the growth of cancer cells, whereas its PLA2 activity promotes the invasion and metastasis of cancer cells." (PMID 36361777, 2022). "On the other hand, low expression levels of PRDX1, PRDX4 and PRDX6 were correlated with C3 subtypes, indicating that they are potential tumor promoters, similar to pan-cancer results." (PMID 34246267, 2021). "Evidence indicates that PRDX6 promotes the migration and invasion of cancer cells during cancer progression." (PMID 32201510, 2020). "Inversely, the invasion and migration of cancer cells with PRDX6 overexpression was remarkably attenuated by PRDX6 knockdown." (PMID 32201510, 2020).